SNORD94 (small nucleolar RNA, C/D box 94)
Synonyms: U94
Gene: Small nucleolar RNA gene on chromosome 2 (86,135,870 to 86,136,006, forward strand). Ensembl gene ENSG00000208772.
Gene Ontology:
Biological process: RNA processing
Cellular component: nucleolus
Homologues: Orthologues: chimpanzee SNORD94 (99% identical), macaque SNORD94 (98% identical), guinea pig SNORD94 (93% identical), mouse Snord94 (93% identical), rabbit SNORD94 (93% identical), pig SNORD94 (91% identical), rat Snord94 (88% identical).
Diseases named in the same sentence as SNORD94 in open-access papers:
SNORD94 is named in the same sentence as 13 diseases in open-access papers, as found by Europe PMC text mining. Sharing a sentence is not in itself a finding about the gene and the disease. The quoted sentences say what the papers report.
pancreatic adenocarcinoma (1 paper, 2025). "In other cancers, SNORD94 has been reported as downregulated in secondary plasma cell leukemia (sPCLs) and in pancreatic adenocarcinoma." (PMID 41283331, 2025).
SNORD94 also shares sentences with these, for which no sentence is quoted: infection (7 papers); tumor (3); breast carcinoma (2); cancer (2); cervical cancer (2); multiple sclerosis (2); prostate carcinoma (2); Autoimmunity (1); diffuse large B-cell lymphoma (1); latent infection (1); plasma cell leukemia (1); Sepsis (1).